PIGF (phosphatidylinositol glycan anchor biosynthesis class F)
Description:
Stabilizing subunit of the ethanolamine phosphate transferase 3 and ethanolamine phosphate transferase 2 complexes that sequentially transfer an ethanolamine phosphate (EtNP) from a phosphatidylethanolamine (PE) to the 6-OH position of the third alpha-1,2-linked mannose and the second alpha-1,6-linked mannose of a 2-acyl-6-[alpha-D-mannosyl-(1->2)-alpha-D-mannosyl-(1->6)-2-phosphoethanolamine-alpha-D-mannosyl-(1->4)-alpha-D-glucosaminyl]-1-(1-radyl,2-acyl-sn-glycero-3-phospho)-1D-myo-inositol (also termed H6) intermediate to generate a 2-acyl-6-[6-phosphoethanolamine-alpha-D-mannosyl-(1->2)-6-phosphoethanolamine-alpha-D-mannosyl-(1->6)-2-phosphoethanolamine-alpha-D-mannosyl-(1->4)-alpha-D-glucosaminyl]-1-(1-radyl,2-acyl-sn-glycero-3-phospho)-1D-myo-inositol (also termed H8). Participates in the tenth and eleventh steps of the glycosylphosphatidylinositol-anchor biosynthesis, in association with PIGO and PIGG, respectively.
Synonyms: PIG-F; OORS
Tractability: Antibody: UniProt predicts a signal peptide or a membrane-spanning region.
Gene: Protein-coding gene on chromosome 2 (46,580,937 to 46,617,055, reverse strand). Ensembl gene ENSG00000151665.
Subcellular location: Endoplasmic reticulum membrane
Pathways (Reactome):
Metabolism of proteins: Synthesis of glycosylphosphatidylinositol (GPI)
Gene Ontology:
Molecular function: protein binding
Biological process: GPI anchor biosynthetic process
Cellular component: endoplasmic reticulum membrane
Genetic constraint (gnomAD): Loss-of-function variants: 1 observed, 5.48 expected, observed/expected ratio (o/e) 0.18, 90% interval 0.064 to 0.87. That is too few expected variants to judge how well the gene tolerates losing a copy. Missense variants: 41 observed, 46.49 expected, observed/expected ratio (o/e) 0.88, 90% interval 0.69 to 1.14. Synonymous variants: 15 observed, 17.32 expected, observed/expected ratio (o/e) 0.87, 90% interval 0.58 to 1.33.
Gene-disease validity (ClinGen):
ClinGen rates the evidence that PIGF causes each of these diseases.
onychodystrophy, osteodystrophy, impaired intellectual development, and seizures syndrome (autosomal recessive): Limited.
Homologues: Orthologues: chimpanzee PIGF (99% identical), dog PIGF (93% identical), pig PIGF (90% identical), guinea pig PIGF (89% identical), mouse Pigf (88% identical), rabbit PIGF (88% identical), rat Pigf (85% identical), macaque PIGF (84% identical), tropical clawed frog pigf (62% identical), zebrafish pigf (53% identical), Drosophila melanogaster PIG-F (21% identical), Caenorhabditis elegans F49E8.8 (18% identical).
Diseases named in the same sentence as PIGF in open-access papers:
PIGF is named in the same sentence as 77 diseases in open-access papers, as found by Europe PMC text mining. Sharing a sentence is not in itself a finding about the gene and the disease. The quoted sentences say what the papers report.
preeclampsia (62 papers, 2012 to 2025). Preeclampsia is a hypertensive disorder of pregnancy that is characterized by new-onset hypertension with proteinuria presenting after 20 weeks of gestation, and depending on mild or severe forms may initially present with severe headache, visual disturbances, and hyperreflexia. "There are already methods for automatically measuring PIGF that have been used to assess the risk of preeclampsia." (PMID 41473191, 2025). "Exposure to O3 during pregnancy was associated with an increased sFlt-1/PIGF ratio, a characteristic feature of preeclampsia." (PMID 40731777, 2025). "Two placenta-derived angiogenic biomarkers, soluble fms-like tyrosine kinase 1 (sFlt-1) and placental growth factor (PIGF) have proved useful as diagnostic and prognostic tests for preeclampsia." (PMID 38883989, 2024). "The results presented here report patients at high and moderate risk of preeclampsia, stratified according to the analysis of sFlT-1/PIGF, sFlT-1, and PIGF and treated." (PMID 39769260, 2024). "In first-trimester screening, the proteins PAPPA-A and PIGF have been successfully utilized to predict the risk of preeclampsia and apply acetylsalicylic acid prophylaxis." (PMID 38256600, 2024). "Abnormal levels of the PIGF angiogenic factor and the sFlt-1/PIGF ratio are often associated with several pregnancy disorders, such as placenta accrete and preeclampsia." (PMID 35248077, 2022). "According to an in vivo study conducted on pregnant mice, exposure to low-dose BPA was associated with developing features similar to preeclampsia, including hypertension, altered levels of sFlt-1/PIGF ratio, and kidney damage." (PMID 34205666, 2021). "The measurement of PIGF can be used for risk stratification and substantially reduces the time to diagnosis of preeclampsia." (PMID 34685589, 2021). "An increase in circulating levels of sFlt1 (soluble FMS-like tyrosine kinase 1) and downregulation of PIGF (placental growth factor) levels are diagnostic markers, which assist in the early diagnosis of preeclampsia." (PMID 34685589, 2021). "Preeclampsia is associated with placental ischemia, which consequently reduces the placental growth factor (PIGF) level, with increased coagulopathy resulting from activation of the fibrinolytic system, platelet activation, and a decrease in platelet count." (PMID 31805880, 2019). "Her sFlt-1/PIGF ratio of 276 (physiological sFlt/PIGF ratio < 33) indicated a high risk of developing preeclampsia in the next 4 weeks." (PMID 30658715, 2019). "Decreased maternal serum levels of PIGF during early gestation correlate with an increasing risk of abnormal pregnancy and, specifically, early-onset preeclampsia." (PMID 26949402, 2016). "High Bb levels and low PiGF concentrations have been associated with later preeclampsia development." (PMID 24987708, 2014). "On the contrary, it was displayed that the reduced level of PIGF below the cutoff value was associated with an increased probability of developing preeclampsia with odds ratio 20 [95% confidence interval 10.2–39.5]." (PMID 24367379, 2013). "Our findings suggest that folic acid may mitigate the risk of preeclampsia through its effects on PIGF levels." (PMID 41473191, 2025). "In May 2023, the U.S. Food and Drug Administration approved a biomarker screening test (sFlt-1/PIGF) at 24–34 weeks of gestation, shown to have a 94% sensitivity and 75% specificity, to identify patients at high risk of severe preeclampsia." (PMID 38883989, 2024). "In this review, sFlt-1 and PIGF are two biomarkers that have been implicated in the development of preeclampsia and have also been investigated as predictors for adverse outcomes related to preeclampsia." (PMID 37007771, 2023). "Moreover, treatment with PFOS also reduced the expression of PIGF, a potent angiogenic factor, which is implicated in preeclampsia and IUGR." (PMID 34203907, 2021).
preeclampsia (continued). "Increased sFlt1 and decreased PIGF-mediated angiogenic imbalance suppress the expression and secretion of factor H from placental endothelial cells, further activating the CS to cause endothelial cell damage and systemic vascular dysfunction, hypertension, and proteinuria during preeclampsia." (PMID 40904461, 2025). "PIGF, or an increased sFLT1/PIGF ratio have an association with FGR, though they are far more strongly linked with preeclampsia." (PMID 40497429, 2025). "Soluble Flt-1 is encoded by an alternatively spliced transcript of sFlt-1 is an antagonist of VEGF and PIGF and is up-regulated in preeclampsia." (PMID 38910142, 2025). "Women with preeclampsia exhibit urinary excretion of the MAC because of an antiangiogenic state (high circulating sFlt1 and low PIGF and VEGF levels) associated with severe preeclampsia." (PMID 40904461, 2025). "Another study has indicated an increase in placental sFlt1 and PIGF in women with preeclampsia, which increases maternal circulating sFlt1 and falls post-delivery." (PMID 40904461, 2025). "It was established previously that serum expression of PIGF shows significant decrease in women who later had preeclampsia, as early as 12 weeks of pregnancy; however serological marker sFlt-1 only starts to elevate in high-risk patient after 20 weeks." (PMID 40061129, 2025). "The decreased plasma ficolin-2 level of women with preeclampsia positively correlates with circulating placental growth factor (PIGF) and inversely correlates with circulating sFlt1." (PMID 40904461, 2025). "This discovery was followed by a number of studies using the sFlt-1/PIGF ratio to diagnose preeclampsia, and then also to predict preeclampsia and adverse outcomes." (PMID 38883989, 2024). "The most notable biomarkers are sENG, sFlt1, and PIGF, which have high sensitivity and specificity for early detection and prognosis of preeclampsia." (PMID 38419047, 2024). "The levels of sFlt-1 and the sFlt-1/PIGF ratio were found to be higher in preeclamptic patients than in the normal group, and can be used as markers for the differential diagnosis of preeclampsia." (PMID 39194706, 2024). "sFlt-1 mRNA is increased (and PIGF proportionately decreased) in placentas of individuals with preeclampsia, and serum sFlt-1 levels are almost five times higher in severe preeclampsia compared with normotensive pregnancies." (PMID 38883989, 2024). "Fms-like tyrosine kinase (sFtl-1) is a circulating antagonist for vascular growth factors (VEGF, PIGF), circulating levels in preeclampsia being increased due to placental ischemia several weeks before clinical onset, sometimes starting in the first trimester." (PMID 36766955, 2023). "The mean value of the sFtl-1/PIGF ratio of pregnant women with preeclampsia was 209.2 pg/mL, while in the gestational hypertension group, the mean value of the sFtl-1/PIGF ratio was 46.08 pg/mL." (PMID 36766955, 2023). "As early as 13–16 weeks of gestation, pregnant women who subsequently develop preeclampsia have lower serum levels of PIGF than the controls, highlighting a potential biomarker for predicting the early onset of preeclampsia." (PMID 37266451, 2023). "The difference between the value of the sFtl-1/PIGF ratio of the group with preeclampsia and the gestational hypertension group was > 67 (pg/mL), with a sensitivity of 86.44% and a specificity of 92.00%." (PMID 36766955, 2023). "Material and Methods: In our study a descriptive and prospective plan was used for analyzing the specific value of the sFtl-1/PIGF ratio in women with preeclampsia and in women with gestational hypertension, depending on the gestational age and severity." (PMID 36766955, 2023). "The aim of this study consists in assessing the clinical utility of the sFtl-1/PIGF ratio in determining the diagnosis and severity of preeclampsia." (PMID 36766955, 2023).
preeclampsia (continued). "This study compared the discriminative ability of sFlt-1, PIGF, sFlt-1/PIGF ratio as continuous, and sFlt-1/PIGF ratio using a binary cut-off of 38 for identifying preeclampsia within 7 days of screening." (PMID 35761268, 2022). "Clinical information on individual preeclamptic patients showing the gestational age, maternal age at delivery, week of preeclampsia diagnosis, sFlt‐1/PIGF ratio, other pathologies, treatment, and additional relevant information." (PMID 35582873, 2022). "A study comparing laboratory parameters in women with preeclampsia found a significant correlation between serum sFlt-1/PIGF ratio levels and systolic (r = 0.35) as well as diastolic (r = 0.30) BP values." (PMID 35329840, 2022). "In real-world clinical practice, the use of PIGF is reported to have a predictive potential for delivery of small for gestational age infants and lower time for preeclampsia diagnosis by clinicians." (PMID 35761268, 2022). "Based on that early/late onset IUGR and preeclampsia are sharing some common pathogenic genes, the ratio sFlt1/PIGF has been clinically applied to screen out IUGR (not only placental insufficiency IUGR) and preeclampsia at the maternal serum protein level." (PMID 35090410, 2022). "Among the other known biomarkers of preeclampsia—sFLT-1, pregnancy-associated plasma protein A (PAPP-A), placental growth factor (PIGF), and endoglin (ENG)—PIGF and PAPP-A were indeed significantly different between normotensive and preeclamptic women." (PMID 36569558, 2022). "It is known that the rise in plasma PIGF levels observed in normal pregnancies is significantly attenuated in pregnancies complicated by preeclampsia." (PMID 33652665, 2021). "In preeclampsia, circulating levels of sFlt1 tend to be increased while circulating PIGF levels are reduced." (PMID 34685589, 2021). "Promising results from previous studies showed that angiogenic (placenta growth factor (PIGF)) and antiangiogenic (soluble fms-like tyrosine kanise-1 (sFlt1)) factors and uteroplacental flows could be used as diagnostic tests for superimposed preeclampsia on CKD." (PMID 32349458, 2020). "In the present study, the concentrations of sFlt-1 and PIGF were significant higher in patients with early-onset preeclampsia (< 34 weeks) than in those with late-onset PE (> 34 weeks)." (PMID 31345176, 2019). "The median (IQR) of sFlt-1/PIGF in the early-and late-onset preeclampsia groups were 313.52 (502.25), and 166.59(195.37)respectively, p = 0.006." (PMID 31022243, 2019). "The sFlt-1/PIGF ratio already increases before the onset of the clinical symptoms and is therefore used as a predictor for preeclampsia with high sensitive and specific values." (PMID 30658715, 2019). "sFlt/PIGF Ratio: The PIGF/sFlt-1 ratio has been brought forward as a possible predictive marker not only for preeclampsia butalso other placenta related disorders such as IUGR or stillbirth." (PMID 31988641, 2019). "Placental growth factor (PIGF) is an angiogenic factor and low concentrations have been observed in pregnant women who develop preeclampsia." (PMID 29587776, 2018). "Preeclampsia patients showed higher sFlt1 and lower PIGF levels than patients with pregnancy-induced-hypertension and gestational proteinuria." (PMID 28388642, 2017). "In most of studies the sensitivity of more than 75% is demonstrated for prediction value of sFlt1 /PIGF ratio especially for early onset preeclampsia." (PMID 26221124, 2015). "As it can be seen the serum levels of sFlt1 are increased in preeclampsia associated with decreased levels of free VEGF and PIGF." (PMID 26221124, 2015). "In humans, serum levels of the angiogenic placental growth factor (PIGF) are reduced in women with preeclampsia." (PMID 24367379, 2013). "The sFlt-1/PIGF ratio at cutoff value of 24.5 was able to predict preeclampsia with sensitivity, specificity, and accuracy of 91.6%, 86.4%, and 87.7%, respectively with OR 67 [95% CI, 29.3–162.1]." (PMID 24367379, 2013).
preeclampsia (continued). "The sFlt-1/PIGF ratio was found to be important for the prediction of both preeclampsia and intrauterine growth restriction (IUGR)." (PMID 24195779, 2013). "PIGF at cutoff value of 138 pg/mL was able to predict preeclampsia with sensitivity, specificity, and accuracy of 85.5%, 77.2%, and 79.3%, respectively, with OR 20 [95% CI, 10.2–39.5]." (PMID 24367379, 2013). "The link between sFLT1 and preeclampsia is sufficiently robust that it is now used as a diagnostic adjunct: a normal sFLT1/PIGF ratio is used to rule out the presence of the condition in women where it is clinically suspected." (PMID 40497429, 2025). "Significant differences were found between the median values of the sFtl-1/PIGF ratio in pregnant women with severe preeclampsia in the early-onset subgroup compared to those in the late-onset subgroup (307 pg/mL, and 98 pg/mL, respectively, p = 0.009 < α = 0.05)." (PMID 36766955, 2023). "PIGF is a pro-angiogenic factor that is reduced in preeclampsia." (PMID 36417467, 2022). "It has been observed that antiangiogenic-soluble fms-like tyrosine kinase-1 (sFlt-1) levels are elevated before the development of preeclampsia (5 weeks before), whereas levels of the angiogenic placental growth factor (PIGF) have been shown to diminish in women with preeclampsia." (PMID 35329840, 2022). "Steady progress has been made to elucidate disease mechanisms on a placental level and molecular markers such as the sFlt-1/PIGF ratio (soluble Fms-like Tyrosinkinase-1/Placental growth factor) have improved prediction for occurrence of preeclampsia." (PMID 35508969, 2022). "Furthermore, free PIGF levels seem to be decreased in preeclampsia mostly because of sFlt-1 binding." (PMID 35761268, 2022). "In some countries, the ratio of sFlt1/PIGF is recommended as diagnostic criterion to differentiate preeclampsia cases from non-preeclamptic pregnancies." (PMID 34685589, 2021). "Moreover, melatonin can repair the endothelial damage from preeclampsia at the placenta level, increasing PIGF, Nrf-2, HO-1 production and reducing critical markers of vascular injury during the pregnancy." (PMID 34867473, 2021). "The involvement of sFlt1 in symptoms of preeclampsia is documented whereas deficiency of PIGF is redundant and does not cause preeclampsia symptoms." (PMID 34685589, 2021). "Preeclampsia is associated with decreased levels of vasodilators, such as nitric oxide (NO) and prostacyclin, as a result of the disproportionate increase in sFlt-1 and decrease in VEGF and PIGF." (PMID 30079067, 2018). "However, a high sFlt-1/PIGF ratio could propose placental dysfunction in preeclampsia, but excessive levels are observed in SARS-CoV-2-infected pregnant women." (PMID 37760899, 2023). "The increased cfDNA coverage within the PIGF gene body and its upstream 5′ UTR region in preeclampsia cases suggests potential transcriptional suppression of PIGF." (PMID 40061129, 2025). "Antwi and colleagues found that predictive ability for gestational hypertension in Ghanaian women improved with the incorporation PAPP-A and PIGF measurements between 8 to 13 weeks of gestation." (PMID 35200708, 2022). "A number of growth factors/cytokines with angiogenic properties have been actively studied in the context of preeclampsia, including HIF-1α, PIGF, TGF-β, and VEGF." (PMID 33652665, 2021). "Conversely, pro‐angiogenic factors, such as VEGF and PIGF, are markedly decreased in patients with PPCM or PIH/preeclampsia." (PMID 32529705, 2020). "In contrast to the pattern of the antiangiogenic factors, pro-angiogenic PIGF and VEGF are present in decreased concentrations in preeclampsia even before clinical manifestation occurs." (PMID 30079067, 2018). "Though the placenta normally produces sFlt-1 and sEng, these factors are produced in higher amounts from hypoxic placentae in pregnancies affected by preeclampsia and interact with PIGF and VEGF in women destined to develop preeclampsia." (PMID 23690796, 2013).
preeclampsia (continued). "The sFlt-1/PIGF ratio has been reported to have higher accuracy in differentiating preeclampsia patients from those without preeclampsia." (PMID 39194706, 2024). "Patients pre-destined to develop preeclampsia exhibit no significant increase in sFLT1/PIGF and sENG/PIGF ratios until 20 weeks of gestation." (PMID 39093387, 2024). "The authors differentiated both conditions using normal PIGF testing, which ruled out preeclampsia with a very high negative predictive value." (PMID 37760899, 2023). "PIGF is a VEGF related molecule that is expressed at high levels by trophoblast cells in the placenta and it is known to play an important role in the pathophysiology of preeclampsia." (PMID 33652665, 2021). "In particular, analysis of angiogenic factors throughout the pregnancy has shown elevated maternal concentrations of sFlt-1 and sFlt-1/PIGF ratio in multiple compared to singleton pregnancies without preeclampsia." (PMID 27835686, 2016). "Interestingly, significantly lower PIGF levels, but with higher sFLT1 and sENG concentrations, have been demonstrated before gestation week 30 in the serum or plasma of pregnant women who have developed preeclampsia if compared with pregnant women who have not develop this disease." (PMID 24987708, 2014).